INS (insulin)
Diseases named in the same sentence as INS in open-access papers (continued):
Sharing a sentence is not in itself a finding about the gene and the disease.
Insulin resistance (continued). "In younger rats, blood insulin level is elevated (due to insulin resistance) compared with the non-diabetic control, to finally decline with ageing (as a result of progressive β-cell failure) below physiological values." (PMID 31623226, 2019). "In most cases, insulin resistance is present and precedes the development of T2DM by increasing the requirements for insulin, leading to insulin insufficiency in individuals whose β-cells have limited secretory reserve and is most often related to obesity, ageing, and physical inactivity." (PMID 31438580, 2019). "The decrease in plasma insulin/HOMA-IR and the improvement in glucose tolerance suggest that DS-EA may improve insulin resistance." (PMID 30841605, 2019). "Similarly, inhibition of insulin signaling decreased KRT5 and KRT10 protein levels, indicating that expression of these molecules is directly influenced by insulin resistance." (PMID 31581253, 2019). "In literature, the studies aimed to define DM insulin resistance driving mechanisms provided evidences that in addition to aberrant splicing of INSR gene, defects in post-receptor insulin signalling might contribute to this feature of the disease." (PMID 30901379, 2019). "The NIDDM patients had less insulin resistance and secretion disorder, normal or slightly lower insulin level in plasma, and the internal target tissue of the body was not sensitive to insulin response." (PMID 31072232, 2019). "Insulin resistance (IR) is a pathological condition in which a target cell or a target organ fails to respond normally to insulin, so that insulin is unable to stimulate glucose disposal, which is a serious risk factor leading to the onset of T2DM." (PMID 31920677, 2019). "Indeed, vitamin D improves insulin resistance and T2DM by affecting insulin sensitivity, β-cell function or both." (PMID 31635074, 2019). "To further investigate whether the PCS extract could ameliorate MGO-induced insulin resistance in vivo, we examined the effects of the PCS extract on the insulin signaling pathway in the liver tissue by western blotting." (PMID 31976027, 2019). "It has been shown that six-day resistin treatment elevated plasma glucose and insulin levels, as well as HOMA-IR in wild-type mice, confirming that resistin may induce insulin resistance." (PMID 31013835, 2019). "Reduced fasting total FFA levels in insulin-resistant patients, unchanged in patients without insulin resistance but with hypercholesterolemia." (PMID 31466350, 2019). "Despite the fact that adipose tissue is not the main tissue responsible for insulin-dependent glucose uptake, it appears to be the main tissue responsible for the induction of systemic insulin resistance." (PMID 31013835, 2019). "It has been shown that chocolate or cocoa reduced insulin and fasting insulin after glucose challenge and improved insulin resistance, while there was no change on fasting glucose and glycated hemoglobin (HbA1c)." (PMID 30931309, 2019). "Insulin resistance (IR) is a pathological condition, in which glucose uptake, metabolism, and storage are not adequately controlled by insulin." (PMID 30881473, 2019). "Using TyG index as the insulin resistance index does not require the measurement of serum insulin levels (an expensive test that is not available in many laboratories)." (PMID 30934836, 2019). "We noted that IGFBP7 was up-regulated while IRS-3 was down-regulated and involved in insulin signaling pathway, implying that IGFBP7 may induce insulin resistance by inhibiting IRS-3." (PMID 31805951, 2019). "In contrast, numerous studies have consistently shown that nondiabetic morbidly obese subjects exposed to a glucose load can clearly increase insulin secretion without achieving blood glucose clearance due to a marked insulin resistance." (PMID 31183389, 2019).
Insulin resistance (continued). "These insulin-mediated alterations in tumor glucose metabolism translated to differences in tumor size: high fat feeding accelerated E0771 tumor growth, whereas the reversal of insulin resistance and hyperinsulinemia with CRMP reversed this effect through an insulin-mediated mechanism." (PMID 31867105, 2019). "The involvement of the nonessential amino acid serine in the regulation of insulin sensitivity opened lines of research into the targeting of PSAT1 for treatment of insulin resistance and type 2 diabetes in mice." (PMID 31234367, 2019). "Furthermore, TNMD expression promotes preadipocyte proliferation and adipogenesis in SGBS adipocytes, and they improved insulin sensitivity in Tnmd transgenic mice, which suggesting the protective role of TNMD in VAT to alleviate insulin resistance in obesity." (PMID 30850679, 2019). "However, in cells transfected with DYRK1A, moderate insulin responsiveness was observed with increased levels of Ser-473 AKT phosphorylation (288.5 ± 4.0% of control, p < 0.0001), indicating DYRK1A ameliorate insulin resistance (lane 8 versus 7)." (PMID 31723029, 2019). "Visfatin-induced inflammation and insulin resistance were regulated by JAK2/STAT3 and IKK/NF-κB signaling; together with AG490 or Bay 7082, visfatin significantly reduced mRNA levels of IL-6, TNF-α and IL-1β and rescued insulin signaling." (PMID 31396538, 2019). "However, according to the homeostatic model assessment of insulin resistance [HOMA-IR], sensitivity to insulin would improve among persons consuming lower GI vs. higher GI diets across a range of fasting blood glucose values >6 mmol/L." (PMID 31242690, 2019). "Inflammation and insulin resistance are closely related and inflammatory cytokines such as TNF-α, interleukin (IL)-6, IL-1, and IL-8 may inhibit insulin signaling via multiple mechanisms." (PMID 31331342, 2019). "As soon as insulin resistance appears, the pancreas produces more insulin to maintain normoglycemia." (PMID 30678043, 2019). "At the end of the experimental period, diabetic control rats showed significant increase in plasma glucose, homeostatic model assessment of insulin resistance (HOMA-IR), glycosylated hemoglobin (HbA1c) with concomitant decrease in plasma insulin, total hemoglobin and body weight." (PMID 31142215, 2019). "Moreover, insulin resistance in the KTR group was significantly higher than that in the HC group, and insulin secretion in the KTR group was also higher than that in the HC group." (PMID 31252561, 2019). "We hypothesize and validate that insulin ineffectively regulates FFA and higher FFA may reduce glucose transport, which leads to a harmful cycle promoting hyperglycemia and developing insulin resistance in the long-term." (PMID 31499737, 2019). "Moreover, inhibition of GRK2 activity leads to increased insulin sensitivity in in vitro and in vivo models of insulin resistance, demonstrating that GRK2 mediates insulin resistance through a kinase-dependent mechanism." (PMID 30934608, 2019). "In summary, vitamin D supplementation in T2D patients can improve HbA1c, insulin resistance, and insulin in short-term intervention, but the impact on the FBG is not significant." (PMID 30946322, 2019). "Alternatively, perhaps in GDM the insulin resistance is an effect of impairment of insulin action, rather than insulin secretion (similar to type 2 DM patients) with declining of insulin receptors and impairing intracellular glucose transport." (PMID 31419950, 2019). "Insulin resistance is due to a reduced responsiveness of target tissues to normal circulating levels of insulin." (PMID 31575072, 2019). "We divided the obese children into an insulin resistance group and a non-insulin resistance group according to insulin HOMA-IR z-scores to evaluate the potential correlations of visfatin and vaspin with insulin resistance." (PMID 31771561, 2019).
Insulin resistance (continued). "Despite high free fatty acid plasma levels, plasma glucose and insulin levels did not change, and animals exhibited a delayed ability to eliminate glucose from the circulation as well as insulin resistance." (PMID 31330823, 2019). "Although insulin resistance has been well-recognized in PCOS, some observations suggest that lean patients with PCOS may have normal insulin sensitivity." (PMID 31507635, 2019). "Average blood Glucose, Insulin and Homeostatic Model Assessment for Insulin Resistance (HOMA-IR) values were not significantly different, although the mean values for each parameter were greater in PCOS samples." (PMID 30904021, 2019). "In vivo human studies have demonstrated a worsening of insulin resistance with olanzapine and aripiprazole independent of any change in weight or body mass, suggesting that antipsychotics have a direct effect on insulin sensitivity [31•]." (PMID 31478094, 2019). "Here, we have shown that RDX8940 is a potent, selective, and minimally systemic oral TGR5 agonist that induces GLP-1, GLP-2, and PYY secretion from mouse intestinal L cells and improves liver steatosis and insulin sensitivity in a model of NAFLD and mild insulin resistance." (PMID 30605011, 2019). "ERK phosphorylation was also not different, indicating that insulin resistance induced by HFD was sufficient to abrogate the difference in insulin signaling observed between controls and M-p110αKO on chow diet (CD)." (PMID 31363081, 2019). "HOMA-Adiponectin was validated as a surrogate measure of insulin resistance in Japanese adults, and consistent with our results, studies in adults have found an inverse correlation between the HOMA-Adiponectin and the clamp-derived insulin sensitivity." (PMID 30908521, 2019). "In conclusion, there are two groups having obviously different causes for the development of GDM in the Japanese population, and the proportion of leaner GDM women who have impaired insulin secretion and no increase in insulin resistance is relatively high." (PMID 31275653, 2019). "Insulin profile (HOMA-IR, QUICKI) signified increase in insulin resistance in OCP treated group." (PMID 31308416, 2019). "First, there was no data regarding plasma insulin and insulin resistance status in the study population." (PMID 31281839, 2019). "The absence of increase in insulin levels in the HF+STZ model is agreement with the lack of insulin resistance in this group." (PMID 31141900, 2019). "We did not observe significant differences in maternal insulin levels at late gestation, change from baseline, and cord blood C-peptide, which were examined as markers of insulin resistance." (PMID 30998227, 2019). "IRS-3 was down-regulated and involved in insulin signaling pathway, implying IRS-3 may induce insulin resistance of NAFLD." (PMID 31805951, 2019). "For example, low vitamin D levels are correlated with several markers of insulin resistance such as plasma glucose, insulin, HOMA-IR and adiponectin in non-diabetic adults." (PMID 30609782, 2019). "Decreased IRS-1 serine phosphorylation is associated with negative effects on the insulin signaling pathway and has been described in connection with TNF-α-induced insulin resistance." (PMID 30863203, 2019). "Homeostatic model assessment index of insulin resistance (HOMA-IR), a method used to assess β-cell function and insulin resistance using fasting glucose and insulin concentrations, also significantly decreased in response to HON treatment, compared to the CON group." (PMID 31075962, 2019). "Common findings in T2D are hyperglycemia and insulin resistance, meaning that peripheral tissues do not respond normally to insulin in order to take up glucose from the blood." (PMID 31275108, 2019). "This paradox in hepatic insulin resistance is that insulin fails to suppress hepatic glucose production, yet it continues to stimulate lipogenesis, resulting in hyperglycemia, hyperlipidemia, hepatic steatosis, and type 2 diabetes." (PMID 30642126, 2019).
Insulin resistance (continued). "In the normal situation, insulin stimulates glucose (Glc) uptake by both muscle and fat cells, the process that was distorted in the absence of insulin or in insulin resistance." (PMID 31856203, 2019). "According to the reduced SNCA expression in the muscle cell following insulin resistance, the SNCA overexpression may improve the insulin-resistant cell response to insulin." (PMID 31827624, 2019). "Insulin-induced Akt phosphorylation was attenuated in adipose tissue of HuRAKO mice, indicating that HuR ablation in adipocytes could exacerbate HFD-induced insulin resistance in adipose tissue." (PMID 31147543, 2019). "Nod1beta-cko and Rip2beta-cko mice were not more insulin resistant compared with control mice, excluding the possibility that the glucose intolerance in Nod1beta-cko and Rip2beta-cko mice was due to insulin resistance." (PMID 31201384, 2019). "In contrast to HFHSD, HFHFrD did not lead to β-cell insulin resistance but led to impaired liver insulin sensitivity." (PMID 29957055, 2019). "Type 2 diabetes mellitus (T2DM), recognized as a global epidemic by the World Health Organization, is a long-term metabolic disorder characterized by high blood glucose, insulin resistance, and relative lack of insulin." (PMID 31447785, 2019). "When appropriate insulin secretion is not achieved in the pancreas, hyperglycemia and insulin resistance occur." (PMID 31541119, 2019). "SGLT2 inhibitors do not lower insulin resistance or improve insulin secretion (the major pathological defects in type 2 DM) and accordingly represent a new therapeutic option." (PMID 31491943, 2019). "We analyzed the HOMA-IR score, and the improvement of insulin resistance in type 2 diabetic mice after treatment with Ad-GLP-1-hUC-MSCs may be related to the rapid decline in blood glucose levels and increased insulin secretion in mice." (PMID 31949438, 2019). "DM is a complex metabolic disorder characterized with the functional impairment or a lack of insulin-producing β-cells, alone or in combination with insulin resistance." (PMID 31557941, 2019). "Due to the lack data of serum insulin level, the association between TG/HDL-C and insulin resistance was not investigated in the present study." (PMID 30711017, 2019). "In mice, administration of exogenous TNF-α could lead to insulin resistance, conversely neutralization of TNF-α improved insulin sensitivity." (PMID 31736870, 2019). "In the present study, all the HON treatments, except for the high dose of HON on male mice, resulted in a significant reduction in fasting glucose and insulin levels along with a decrease in HOMA-IR in HFD-fed mice (P < 0.05), suggesting that HON can improve insulin resistance." (PMID 31921106, 2019). "We determined that insulin-stimulated phosphorylation of AS160 on serine-588, threonine-642, and serine-666 (but not serine-318 or 751) were impaired in conjunction with the whole-body insulin resistance observed with advancing age." (PMID 31684154, 2019). "T2DM is due to insulin resistance in the target tissue and a relative lack of insulin secreted by islet β-cells, and is mainly affected by the combination of genetic susceptibility and lifestyle factors." (PMID 31557941, 2019). "In addition, adipose tissue specific insulin resistance, assessed using ADIPO-IR, decreased significantly following the diet intervention, further supporting our model’s prediction of improved insulin sensitivity following caloric restriction." (PMID 31581241, 2019). "Twelve weeks of spontaneous exercise and/or a HF/HS diet did not significantly change fasting plasma glucose, plasma insulin, and homeostatic model assessment of insulin resistance (HOMA-IR) index." (PMID 30634469, 2019). "Another suggested mechanism is that central resistin might induce hypothalamic insulin resistance through the impairment of adiponectin and FGF21 signaling known as insulin-sensitizing hormones." (PMID 30906281, 2019).
Insulin resistance (continued). "Fasting plasma glucose (FPG) levels, fasting insulin levels, and homeostasis model assessment-insulin resistance (HOMA-IR) were higher in NAFLD subjects than in non-NAFLD subjects in the young-age and middle-age groups." (PMID 31862937, 2019). "Homeostatic model assessment for insulin resistance (HOMA-IR) index of the FvF treated group was significantly lower than that of the model group, which indicated that FvF significantly decreased the fasting insulin level in mice with MetS and relieving IR." (PMID 31547311, 2019). "The absence of ATM in mice affects hepatic insulin sensitivity and promotes atherosclerosis, suggesting the involvement of processes that link hepatic insulin resistance and vascular disease." (PMID 31384309, 2019). "During the progression of insulin resistance, insulin fails to suppress hepatic glucose production yet continues to drive excess lipid synthesis, leading to hyperglycemia, hyperlipidemia, and NAFLD9." (PMID 31873167, 2019). "From the aspect of decline of insulin secretion, the reduction of Cdc42 suppresses the activity of PAK-1 and may promote insulin resistance." (PMID 30621321, 2019). "Insulin resistance was lowered 51–36% irrespective of any significant (P > 0.05) changes in insulin sensitivity throughout the treatments." (PMID 30728837, 2019). "Aligned with the recently identified role of APOC3 in insulin resistance, HOMA-IR, plasma insulin levels, body weight, and adiposity correlated positively with HDL-associated APOC3 levels (r = 0.50, P = 0.00017; r = 0.44, P = 0.0015; r = 0.23, P = 0.048; r = 0.26, P = 0.021, respectively)." (PMID 30622162, 2019). "Saturated ceramides are speculated to have adverse effects on insulin sensitivity; however, HOMA-IR, a surrogate measure of insulin resistance, remained unchanged after HIIT despite the reduced content of saturated ceramides." (PMID 30871020, 2019). "Third, we did not have sufficient biochemical data such as insulin levels to directly address the relationship between S14 and insulin-resistance in this study." (PMID 30763384, 2019). "Unexpectedly, iNOS KO did not protect from HFD-induced insulin resistance even at 1.5 weeks, although the deleterious effects of iNOS on insulin sensitivity have been widely described in mice." (PMID 30716103, 2019). "The predominant type 2 diabetic phenotype is characterized by peripheral insulin resistance, whereby insulin no longer effectively stimulates the uptake of glucose into muscle and adipose tissue." (PMID 31920989, 2019). "We noted that there was no increase in serum insulin concentrations in HFD-fed mice with insulin resistance." (PMID 30054493, 2018). "When systematic insulin resistance is established after 13 weeks on HFD demonstrated by the glucose and insulin tolerance tests, attenuated insulin-induced glucose uptake IBAT of AD mice suggests that IBAT is more vulnerable to HFD under an AD genetic background." (PMID 30096853, 2018). "Interestingly, compared to women with regular cycles (matched for age and BMI), insulin resistance in women with PCOS is worse, suggesting an influential role for androgen excess in the insulin resistant phenotype." (PMID 30377436, 2018). "In addition to its regulation of insulin signaling at the receptor level, fetuin-A also modulated FFA-mediated inflammation of the β-cells in the pancreas, thereby contributing to insulin resistance at this level also." (PMID 30060600, 2018). "Mutant forms of FAK impair insulin signalling in HepG2 cells and tail-vein injection of siRNA against the FAK gene (PTK2) leads to insulin resistance, concomitant with reduced protein kinase B (PKB, also known as Akt) phosphorylation in mouse models of diabetes." (PMID 29022062, 2018). "This insulin-induced hyper-phosphorylation of AKT1 and GSK-3β was significantly reduced in KO mice as assessed using western blotting, which implied that mild insulin resistance was induced in KO mice." (PMID 30485307, 2018).